NEDD4 (NEDD4 E3 ubiquitin protein ligase)
Diseases named in the same sentence as NEDD4 in open-access papers (continued):
Sharing a sentence is not in itself a finding about the gene and the disease.
asthenospermia (1 paper, 2022). "The intersection among two groups of hub genes included COPS7A, CUL3, KLHL7, and NEDD4, which can be considered the main key genes in asthenozoospermia." (PMID 36471356, 2022). "A Venn analysis was used to identify four key genes based on two methods, including COPS7A, CUL3, KLHL7, NEDD4, which may be potentially important genes in asthenozoospermia." (PMID 36471356, 2022). "The mRNA expression of COPS7A was upregulated in patients with asthenozoospermia, but the expression of CUL3, KLHL7, and NEDD4 was downregulated in these patients." (PMID 36471356, 2022). "Finally, we found that the COPS7A was significantly upregulated in patients with asthenozoospermia, but CUL3, KLHL7 and NEDD4 were significantly downregulated compared with normal samples." (PMID 36471356, 2022). "A western blotting assay using 16 semen samples (including 8 asthenospermia and 8 normal samples) revealed similar results, indicating COPS7A was significantly upregulated in patients with asthenozoospermia, but CUL3, KLHL7 and NEDD4 were significantly downregulated compared with normal samples." (PMID 36471356, 2022).
atherosclerosis (1 paper, 2020). A disease characterized by the build-up of fatty material and calcium deposition in the arterial wall resulting in partial or complete occlusion of the arterial lumen. "In addition, methylation of human NEDD4 gene promoter is remarkably enhanced in individuals with atherosclerosis." (PMID 33110392, 2020). "Thus, dysregulated or dysfunctional NEDD4-1 E3 ligase could contribute to vascular calcification in VSMCs through induction of bone generating signals in the process of atherosclerosis progression." (PMID 33110392, 2020).
autoimmune disease (1 paper, 2025). A disorder resulting from loss of function or tissue destruction of an organ or multiple organs, arising from humoral or cellular immune responses of the individual to their own tissue constituents. "Nedd4 is a crucial E3 ubiquitin ligase for RORγt in the regulating Th17 cell development and offers potential therapeutic benefits for treating Th17-mediated autoimmune diseases." (PMID 39972304, 2025).
Autoimmunity (1 paper, 2025). The occurrence of an immune reaction against the organism's own cells or tissues. "To test whether Nedd4 regulates Th17-mediated autoimmunity we used EAE as a model in which the pathogenic Th17 response has been shown to play a key role in disease development." (PMID 39972304, 2025). "Furthermore, we investigated the influence of Nedd4 deficiency on Th17-mediated autoimmunity through experimental autoimmune encephalomyelitis (EAE), a mouse model of MS." (PMID 39972304, 2025). "These uncharted aspects inspire us to explore the potential role of Nedd4 in Th17-mediated autoimmunity." (PMID 39972304, 2025). "Nedd4 has been shown to positively regulate T cell activation, but the roles of Nedd4 in T helper (Th) cell differentiation and autoimmunity are unknown." (PMID 39972304, 2025). "The HECT E3 ubiquitin ligase Nedd4 has been shown to positively regulate T cell responses, but its role in T helper (Th) cell differentiation and autoimmunity is unknown." (PMID 39972304, 2025). "Therefore, our study identified a novel function for Nedd4 in Th17 cell differentiation, and Th17-mediated autoimmunity." (PMID 39972304, 2025).
brain injury (1 paper, 2016). Acute and chronic (see also brain INJURIES, CHRONIC) injuries to the brain, including the cerebral hemispheres, CEREBELLUM, and brain STEM. "For example, exosomes from primary neurons traffic Nedd4-WW (neural precursor cell expressed, developmentally down regulated) domain-binding protein 5 (N4WBP5), which interacts with the ubiquitin ligase Nedd4 and mediates neuroprotection in models of traumatic brain injury." (PMID 26861302, 2016).
brain tumor (1 paper, 2018). "Whereas simultaneous overexpression of Nedd4 and Ndfip barely exhibited any effect on brain tumor phenotype caused by vps35 mutation, coexpression of Su(dx) and Ndfip indeed led to a complete rescue of the supernumerary neuroblast phenotype in vps35 mutants." (PMID 30176986, 2018).
colitis (1 paper, 2024). Inflammation of the colon. "In addition, a prior study has implicated NEDD4 in mediating Nrf2 to regulate HO-1– and DSS-induced colitis." (PMID 39688910, 2024).
congenital heart disease (1 paper, 2026). A heart disease that is present at birth. "We further identify a new NEDD4 variant underlying human congenital heart disease." (PMID 41571667, 2026).
emphysema (1 paper, 2009). "Gene expression profiling of lung from emphysema patients identified seven candidate genes associated with emphysema severity including COL6A3, SERPINF1, ZNHIT6, NEDD4, CDKN2A, NRN1 and GSTM3." (PMID 19723343, 2009). "The candidate genes (CDKN2A, GSTM3, COL6A3, SERPINF1, NRN1, NEDD4 and ZNHIT6) had ontologies that were relevant to emphysema progression, including cell cycle regulation (CDKN2A), collagen (COL6A3), anti-angiogenesis (SERPINF1) and oxidative stress (GSTM3)." (PMID 19723343, 2009).
epilepsy (1 paper, 2017). A brain disorder characterized by episodes of abnormally increased neuronal discharge resulting in transient episodes of sensory or motor neurological dysfunction, or psychic dysfunction. "Such medication might therefore be specifically useful for epilepsy patients who carry mutations in Nedd4-2." (PMID 28212375, 2017).
epithelioid sarcoma (1 paper, 2022). An aggressive malignant neoplasm of uncertain differentiation, characterized by the presence of epithelioid cells forming nodular patterns. "Taken together, the overall features were considered to be unclassified malignant cutaneous spindled and epithelioid sarcoma with a novel SS18::NEDD4 fusion gene." (PMID 35639915, 2022). "Herein, we describe an aggressively behaving malignant cutaneous spindled and epithelioid sarcoma harboring an SS18::NEDD4 gene fusion in a 60‐year‐old female." (PMID 35639915, 2022). "Herein, we report a case of an unclassified malignant cutaneous spindled and epithelioid neoplasm in a 60‐year‐old female that resembled an epithelioid sarcoma (ES) and harbored a rare SS18::NEDD4 gene fusion." (PMID 35639915, 2022). "In summary, we report a unique case of previously unclassified cytokeratin positive malignant cutaneous spindled and epithelioid sarcoma with aggressive behavior, harboring an SS18::NEDD4 fusion." (PMID 35639915, 2022).
fibrosis (1 paper, 2024). the formation of excess fibrous connective tissue in an organ or tissue in a reparative or reactive process. "However, in 4 and 5-mo-induced conditional Nedd4-2−/− mice in vivo micro-CT fibrosis scores were significantly elevated compared with control mice." (PMID 39437758, 2024).
filariasis (1 paper, 2019). "PBMC from human filariasis patients upregulate anergy-associated ubiquitin ligases, including Nedd4, while Th2 dysfunction in murine schistosomiasis is dependent upon GRAIL." (PMID 31815932, 2019). "Immune suppression during filariasis and other helminth infections is associated with increases in T cell anergy markers, including upregulation of the E3 ubiquitin ligases Nedd4, Itch, C-cbl, Cbl-b, and GRAIL." (PMID 31815932, 2019).
Flavivirus Infections (1 paper, 2020). Infections with viruses of the genus FLAVIVIRUS, family FLAVIVIRIDAE. "In other flavivirus infections, suppression of autophagy mediated by E3 ligases such as Nedd4 facilitated the replication of JEV." (PMID 31971978, 2020).
gallbladder carcinoma (1 paper, 2022). "A study highlighted NEDD4 as an invasion-associated molecule in gallbladder carcinoma and demonstrated that at the transcriptional level NEDD4L regulates MMP-1 (Matrix metalloproteinase-1) and MMP-13 expression, which is overexpressed at an early stage of tumor invasion in various malignant tumors." (PMID 36293239, 2022). "For example, NEDD4 has also been involved in the development of gallbladder carcinoma, which is an aggressive cancer with a high rate of invasiveness that continues to have a poor prognosis, with a less than 10 percentage overall survival rate." (PMID 36293239, 2022).
gastric cardia carcinoma (1 paper, 2018). A carcinoma that arises from epithelial cells of the cardia of stomach. "Our previous studies observed that NEDD4 is overexpressed in gastric cardia carcinoma and significantly correlated with both local and remote metastasis and reversely associated with patient’s survival." (PMID 29455656, 2018).
gram-negative bacterial infections (1 paper, 2023). Infections caused by bacteria that show up as pink (negative) when treated by the gram-staining method. "Previous studies suggested that E3 ubiquitin ligase NEDD4 is a key negative regulator for caspase-11 mediated pyroptosis in response to gram-negative bacterial infection and acute liver injury." (PMID 36732831, 2023).
hematoma (1 paper, 2024). A hematoma is a collection of blood from a vascular structure into an extravascular space. "Furthermore, the impact of Nedd4 overexpression was evaluated through analyses of hematoma area, ferroptosis, and neurobehavioral function." (PMID 38634270, 2024).
HIV-1 infection (1 paper, 2017). The type species of lentivirus and the etiologic agent of acquired immunodeficiency syndrome (AIDS). "Along the same line of thought, measurement of virus production in cells that had been treated with siRNA against NEDD4 or MARCH8 did not allow us to draw any conclusions due to the low permissiveness of these cells to HIV-1 infection." (PMID 28320822, 2017).
Hyperglycemia (1 paper, 2022). An increased concentration of glucose in the blood. "The decreased expression of NEDD4 also prevented MSC-sEV to alleviate hyperglycemia-induced retinal apoptosis." (PMID 35841055, 2022). "We found that MSC-sEV treatment reversed hyperglycemia induced the decreased NEDD4 expression in vivo." (PMID 35841055, 2022).
Hyperkeratosis (1 paper, 2017). Hyperkeratosis is a histopathological term defining a thickened stratum corneum and may be present in many different skin conditions, with many possible overlaps. "NEDD4 is involved in the ΔNp63α-mediated suppression of nuclear PTEN in basal layer keratinocytes, whereas nuclear PTEN inhibits cell proliferation and mice with a keratinocyte-specific null mutation of Pten reportedly exhibit epidermal hyperplasia and hyperkeratosis." (PMID 28410231, 2017).
Insulin resistance (1 paper, 2025). Increased resistance towards insulin, that is, diminished effectiveness of insulin in reducing blood glucose levels. "In particular, both heterogenous Nedd4 KO (Nedd4+/−) and Itch KO (Itch−/−) mice display improved obese-related insulin resistance, as evaluated by the insulin tolerance test (ITT)." (PMID 41009733, 2025).
Intellectual disability (1 paper, 2023). "For example, human orthologs to fly genes CASK (CASK), Mnb (DYRK1A), Dlg-1 (DLG1), Cdc42 (CDC42), Fmr1 (FMR1, FXR1/2), trio (TRIO), Nedd4 (NEDD4L/NEDD4) and CamKII (CAMK2A/B/D) have been linked to intellectual disability." (PMID 37759179, 2023).
intestinal tumour (1 paper, 2020). "Together, we conclude that loss of Nedd4 and Nedd4l in Apcmin animals promotes intestinal tumour progression by enhancing Wnt activation with increased numbers of ISCs and Paneth cells." (PMID 31867777, 2020). "Nedd4 has been previously reported to enhance growth of Apcmin intestinal tumours, which required deletion of Nedd4 in both intestinal epithelium and the surrounding tissues." (PMID 31867777, 2020).
intracerebral hemorrhage (1 paper, 2024). A cerebrovascular disorder characterized by bleeding into one or both cerebral hemispheres including the basal ganglia and the cerebral cortex. "However, the role of Nedd4 in intracerebral hemorrhage (ICH) remains unknown." (PMID 38634270, 2024).
kidney injury (1 paper, 2025). Trauma to the kidney. "Our study elucidated a novel PRMT1/UBE2m/NEDD4/PPARγ signaling axis that drives renal lipid metabolic dysfunction in CaOx crystal-induced kidney injury." (PMID 40744915, 2025).
lentivirus infection (1 paper, 2023). Virus diseases caused by the Lentivirus genus. "To further explore the function of NEDD4 in GC cells, we engineered two different shRNA sequences against NEDD4 in a doxycycline (Dox)-inducible manner and transfected them into GC cells by lentivirus infection." (PMID 36774408, 2023).
Lewy bodies disease (1 paper, 2016). "Previous studies showed that NEDD4 was upregulated in human nigral neurons containing Lewy Bodies (LBs) from patients diagnosed with Lewy bodies disease (LBD)." (PMID 27494837, 2016).
lymphoma (1 paper, 2019). A malignant (clonal) proliferation of B- lymphocytes or T- lymphocytes which involves the lymph nodes, bone marrow and/or extranodal sites. "In our study, both AS-tDR-008946 and AS-tDR-013492 are upregulated and it may inhibit the expression of NEDD4 through a way similar to miRNA and thus accelerate the progress of lymphoma." (PMID 31775867, 2019).
memory impairment (1 paper, 2023). "Although we have shown that Beclin 1 and PTEN are both the endogenous ubiquitination targets of Nedd4 in the hippocampus, our results do not exclude the possibility that Beclin 1 and PTEN are also the ubiquitination targets of other Nedd family proteins involved in Ndfip1-mediated memory impairment." (PMID 37023120, 2023).
meningioma (1 paper, 2024). A generally slow growing tumor attached to the dura mater. "Another DEG upregulated in GSTM1- meningiomas compared to GSTM1+ tumors is NEDD4, which encodes a member of HECT family of E3 ubiquitin ligases." (PMID 39726707, 2024). "While this model is partially supported by the increases in MAP1LC3C and NEDD4 expression in the GSTM1- meningiomas, future studies will be needed to investigate the various components of this model at both the mRNA and protein level." (PMID 39726707, 2024). "It has been shown that NEDD4 is frequently overexpressed in multiple human cancers and primarily functions as an oncogene in various malignancies, which aligns with its upregulation in recurrent meningiomas." (PMID 39726707, 2024).
muscle atrophy (1 paper, 2021). The loss of muscle tissue due to inactivity or disease. "Interestingly, in skeletal muscle, NEDD4 has been reported to be involved in the generation of atrophy under very specific conditions in skeletal muscle such as in disuse (unloading or denervation)‐induced muscle atrophy." (PMID 33687156, 2021).
myocardial infarct (1 paper, 2023). "In addition, NEDD4 deficiency decreased animal survival and increased myocardial infarct size, no-reflow area, and promoted macrophages infiltration post-MI/R." (PMID 36732831, 2023).
neuropathic pain (1 paper, 2017). Chronic pain caused by damage to nerve fibers. "The E3 ubiquitin ligase Nedd4 is decreased in DRGs of SNI mice, and ribosomal protein Rps25, as well as other ribosomal proteins are downregulated in a model for HIV-associated neuropathic pain." (PMID 29422837, 2017).
neuropathy (1 paper, 2022). A disorder affecting the nervous system that manifests with pain, tingling, numbness, and/or muscle weakness. "Restoring ubiquitination of neuropathy mutant TRPV4 through expression of NEDD4 was able to ameliorate increased channel activity." (PMID 35300980, 2022). "We also confirmed NEDD4-mediated suppression of neuropathy mutant channel activity by examining a second neuropathy-causing mutant (R237L TRPV4) in MN-1 cells." (PMID 35300980, 2022). "In these cells, NEDD4 coexpression reduced GSK101 responses in both WT and R237L neuropathy mutant-expressing cells." (PMID 35300980, 2022).
Obesity (1 paper, 2025). Accumulation of substantial excess body fat. "Several family members, including WWP1, NEDD4, and ITCH, have been evaluated in the context of obesity using KO mice models." (PMID 41009733, 2025).
osteoarthritis (1 paper, 2023). A noninflammatory degenerative joint disease occurring chiefly in older persons, characterized by degeneration of the articular cartilage, hypertrophy of bone at the margins and changes in the synovial membrane. "In the following paragraphs, we will discuss the mechanisms of NEDD4 E3 ubiquitin ligases in osteoarthritis initiation and progression." (PMID 37359559, 2023).
pancreatic ductal adenocarcinoma (1 paper, 2017). An infiltrating adenocarcinoma that arises from the epithelial cells of the pancreas. "This indicates that NEDD4 influences pancreatic ductal adenocarcinoma progression and metastasis through PI3K/Akt signaling pathways." (PMID 28423617, 2017). "However, the function and interactions of NEDD4 and PTEN in pancreatic ductal adenocarcinoma (PDAC) still remains elusive." (PMID 28423617, 2017).
Polydipsia (1 paper, 2021). Excessive thirst manifested by excessive fluid intake. "Nedd4-2Ksp1.3 mice had a significant increase in water intake (polydipsia) and urine (polyuria), which was further increased after a high Na+ diet." (PMID 33854040, 2021).
renal cell carcinoma (1 paper, 2019). "Module 2 included NEDD4, CDC27, UBE2E2, and TCEB1 associated with ubiquitin-mediated proteolysis and renal cell carcinoma pathways." (PMID 31178673, 2019).
seborrheic keratosis (1 paper, 2017). A common benign skin neoplasm usually affecting older individuals. "One seborrheic keratosis (SK14) carried a non-synonymous mutation in GRIK1 (c.1148C>A, p.G383D) and an intronic mutation in NEDD4 (c.3471-1C>T) with a potential effect on splicing (Human Splicing Finder)." (PMID 28410231, 2017).
Skeletal muscle atrophy (1 paper, 2024). The presence of skeletal muscular atrophy (which is also known as amyotrophy). "Another transcript with high module membership in the blue module is NEDD4, which encodes another E3 ubiquitin ligase that appears to be associated with post‐denervation skeletal muscle atrophy in mouse models." (PMID 38649783, 2024).
skin melanoma (1 paper, 2021). "Similarly, NEDD4 expression and activity in various tumors including, skin melanoma is linked to tumorigenesis either by acting as a tumor suppressor or oncogene." (PMID 33962630, 2021). "Taken together, the data demonstrate that NEDD4 plays a critical role in the regulation of IGPR-1 in human skin melanoma." (PMID 33962630, 2021). "Next, we asked whether there is a link between IGPR-1 protein levels and NEDD4 in human skin melanoma cell lines." (PMID 33962630, 2021). "Next, we asked whether high levels of NEDD4 is a contributing factor for the relatively low levels of IGPR-1 in skin melanoma cells." (PMID 33962630, 2021).
squamous carcinoma (1 paper, 2022). "To do this, we performed PLA in HaCaT keratinocytes and A431 squamous carcinoma cells with anti-PINCH-1 and anti-NEDD4 Abs." (PMID 35401828, 2022).
urothelial carcinoma (1 paper, 2023). A malignant neoplasm derived from the transitional epithelium of the urinary tract (urinary bladder, ureter, urethra, or renal pelvis). "In urothelial carcinoma, activated FGFR3 phosphorylates NEDD4 and further regulates Lys48‐linked ubiquitination of PD‐L1 to activate CD8+ T cell infiltration and antitumor activity." (PMID 37143582, 2023).